SNAI1 (snail family transcriptional repressor 1)
Diseases named in the same sentence as SNAI1 in open-access papers (continued):
Sharing a sentence is not in itself a finding about the gene and the disease.
tumor (continued). "Interestingly, FC2 displayed the highest correlation with epithelial cells and showed specific expression of tumor epithelial markers KRT8, KRT10, and KRT18, as well as the EMT markers SNAI1 and SNAI2, suggesting that FC2 may have the tumor‐like aggressive potential." (PMID 34459128, 2021). "The HIF‐1α target genes Vegf, Snai1, and Ccng2 showed reduced expression upon nAb‐CCL2 treatment in the CD group, although this did not lead to significant tumor suppression." (PMID 41160815, 2026). "Third, decreased expression of individual tumor-intrinsic mesenchymal markers was confirmed in HER2 positive biopsies; mesenchymal markers such as CDH2, ZEB1, and SNAI1 showed higher expression in the HER2 negative cohort (p < 0.001)." (PMID 39151279, 2024). "The molecular etiology of EC and the pathogenic role of the demonstrated here overexpression of MYC, NR5A2, SNAI1, and TWIST1 in tumor-adjacent tissues is not clear." (PMID 36140779, 2022). "The deletion of Twist1 or Snai1 alone was not sufficient to suppress EMT, while the deletion of ZEB1 had a greater impact on the tumour phenotype and metastasis." (PMID 33207810, 2020). "A recent study suggested that while SNAI1-induced EMT is not absolutely needed for the physical migration of cells during metastasis, it does contribute to increased tumor survival and drug resistance." (PMID 30034631, 2018). "The coordinated upregulation or, not uncommonly, overexpression of ZEB1, ZEB2, SNAI1, and VIM and the downregulation of CDH1 indicated that EMT was under way, making the tumor cells assume a mesenchymal phenotype." (PMID 25157365, 2014). "Patients with negative SNAI1 and TWIST immunostaining in tumor stroma had a better 5-year disease-specific and overall survival (p = 0.037 and p = 0.014 respectively)." (PMID 21834956, 2011). "SNAI1 enhances production of C-C motif chemokine ligand (CCL) 2, which can subsequently induce EMT signaling in other cells of tumor microenvironment (TME) lacking endogenous SNAI1 while simultaneously contributing to the development of immunoregulatory DC populations." (PMID 38426087, 2024). "A positive correlation was observed between the expression of SNAI1 and WASF2 in the tumor group of the TCGA_LIHC dataset (Pearson’s correlation coefficient r = 0.26, P < 0.0001), but not in the non-tumor group (Pearson’s correlation coefficient r = 0.08, P = 0.55)." (PMID 35477411, 2022). "Expression of genes such as AEBP1, SNAI1, and LOX similarly increased after the first week of tumor progression, although these changes could not be quantitatively compared to week 1 due to undetermined Cq values at this time point." (PMID 34868914, 2021). "Moreover, we report differential PBMC expression profiles that correlate inversely with disease stage (SEMA4A, SNAI1, PLXNA1 and VEGFR3) and can differentiate between the TNBC and non-TNBC tumor subtypes (VEGFR3 and PLXNA1)." (PMID 28607365, 2017). "Notably, other important EMT-related markers such as SNAI1, SNAI2, ZEB1, ZEB2 and TWIST1 at the invasive tumor front were not thoroughly examined in these reported studies." (PMID 26214683, 2015).
cancer (816 papers, 2003 to 2026). A tumor composed of atypical neoplastic, often pleomorphic cells that invade other tissues. "SNAI1 is a well-known mesenchymal marker for inducing cancer cell metastasis and also associated with poor prognosis in multiple cancers." (PMID 39708716, 2025). "For example, EVs from cancer-associated fibroblasts carry transcription factors like SNAI1/ZEB1 or miRNAs (e.g. miR-193a, miR-210 from bone marrow cells) that prime lung cells for invasiveness (via STAT3, Wnt, TGF-β pathways)." (PMID 41311647, 2025). "In normal tissues, the regulation of SNAI1 expression is precise, whereas its deregulation is linked to the advancement of several types of cancer." (PMID 39980566, 2025). "The differentiation status of cancer cells showed a close association with the expression levels of both SNAI1 and OV6." (PMID 39702326, 2024). "Increased expression of the resistance genes ABCG2 and ERBB2, the CSC gene ALDH1A3, as well as the EMT gene SNAI1 after 5-FU treatment in PDSs were linked to ER-negative status of the primary cancer." (PMID 38124067, 2023). "On the other hand, cancer cell resistance to cisplatin chemotherapy is related to the STAT3/Snail Family Transcriptional Repressor 1 (Snail) axis, which is associated with the development of the EMT phenotype of cells and stem-like properties." (PMID 38067351, 2023). "SNAI1 encodes Snail-1 which regulates the mesenchymal transition of cancer, and also pro-metastatic CAFs, while SP1 is critical for the production of various ECM proteins." (PMID 35565326, 2022). "In line with the notion that anti-cancer therapy resistance-associated genes are commonly increased by anti-cancer drugs as a feedback response, we further showed that SNAI1 expression is drastically elevated in in vitro derived TN-resistant TNBC cells." (PMID 33510281, 2021). "It is known that downregulation of E-cadherin by the epidermal growth factor receptor EGFR and the main regulator of EMT, SNAI1, is a prominent hallmark of cancer invasion." (PMID 34557494, 2021). "We also discovered associations between SNAI1 expression and cancer hallmarks and immune cell markers across cancer types." (PMID 33299129, 2021). "We show that triptonide downregulates multiple cancer stem cell-associated genes but upregulates SNAI1 gene expression." (PMID 33510281, 2021). "In cancer, SNAI1 expression has been implicated in high-grade malignancies and correlated with poor prognosis, as it is one of the drivers of cancer progression to metastasis." (PMID 34207850, 2021). "Snail, a transcription factor that signals the EMT in many cancer types, is encoded by the SNAI1 gene." (PMID 35664989, 2021). "Increased levels of SNAI1 also induce the self-renewal program of cancer stem-like cells by upregulating stemness factors that cause drug resistance." (PMID 30736337, 2019). "To elucidate the mechanism underlying how autophagy contributes to SNAI1 degradation in cancer cells, we examined the protein levels of SNAI1 in cancer cells after autophagy was induced by starvation or treatment with rapamycin (100 nM)." (PMID 30736337, 2019). "EMT is a process frequently associated with cancer and it involves multiple regulators, including SNAI1, SNAI2, TWIST1 and ZEB1 as well as their targets." (PMID 30379847, 2018). "B Illustration of the relative gene expression of SNAI1 in the epithelial, leukocyte, and endothelial cells and in the cancer-associated fibroblasts cell population as deposited in the colon cancer profile GSE39396." (PMID 29041931, 2017). "SNAI1 has been implicated in cancer cell survival, cell cycle regulation, apoptosis evasion, cell adhesion, neuro-endocrine differentiation, and chemoresistance." (PMID 24565133, 2014). "Diseases associated with SNAI1 include some malignant tumors." (PMID 38520027, 2024).
cancer (continued). "Interestingly, CTCF sites surrounding SNAI1 are enriched for noncoding mutations in cancer, and SNAI1 was among the top hits within the EMT pathway based on our RNA-seq data." (PMID 36037342, 2022). "Additionally, upregulation of mesenchymal markers such as vimentin (Vim) and Snai1 have been associated with increased cancer malignancy." (PMID 34072345, 2021). "In the studies presented here, we asked whether these reprogramming principles applied in cancer: Does expression of SNAI1 lead to loss of let-7 and gain of stemness?" (PMID 33806868, 2021). "It markedly responds to SP1 and numerous other activating transcription factors such as hypoxia-inducible factor (HIF)-2α and EGR-1, as well as E2F1, -3, and -5, and SNAI1, all of which are associated with increased malignancy in the context of various cancers." (PMID 35008569, 2021). "Likewise, accumulation of SQSTM1/p62 activates the NFκB/RELA pathway, which in turn activates the transcription of ZEB1 and SNAI1 in RAS-mutated cancer cells and fibrotic interstitial lung cells, respectively." (PMID 34944948, 2021). "To examine whether this same association can be observed in cancer cells, we carried out ChIP assays to determine the binding of SNAI1 to the promoter region of various let-7 family members, as defined by previous studies." (PMID 33806868, 2021). "The expression of SNAI1 and E-cadherin is a hallmark of carcinoma development and metastasis." (PMID 34513655, 2021). "To further study the participation of P2X7R in the epithelial-to-mesenchymal transition (EMT), we assessed the effect of stimulating 4T1 cancer cells with BzATP on the expression of genes associated with the mesenchymal (SNAI1, ZEB1, TWIST) or the epithelial (ZO1, CDH1) phenotypes." (PMID 32825056, 2020). "Our results show that the intracellular levels of E-cadherin decrease when cancer cells are starved and are increased by the inhibition of autophagy, suggesting that autophagy-dependent SNAI1 degradation is directly associated with its downstream targets such as E-cadherin." (PMID 30736337, 2019). "Taken together, these studies highlight the fact that cancer therapies should not only target physical migration of cells (EMT), but also prevent cancer cell survival and drug resistance through targeting genes like SNAI1, which are associated with increased chemoresistance." (PMID 30034631, 2018). "Indeed, the intensity of SNAI1 was decreased in starved cells but increased after treatment with chloroquine, suggesting that the intracellular levels of SNAI1 are specifically regulated by autophagy and functionally associated with the regulation of cancer progression." (PMID 30736337, 2019). "The epithelial-mesenchymal transition (EMT) drives cancer progression, regulated by transcription factors (TFs) such as SNAI1, SNAI2, ZEB1, ZEB2, and TWIST." (PMID 41481650, 2026). "In head and neck tumour cells (CAL27), exposure to IL-6 cytokines upregulated SNAI1 protein levels and enhanced cancer cell migration." (PMID 40371393, 2025). "SNAI1 encodes for SNAIL1, a master regulator of epithelial-to-mesenchymal transition (EMT) that promotes aggressive phenotypes in cancer." (PMID 40465706, 2025). "This elevation in USP47 expression contributes to cancer-related phenotypes through stabilizing Snai1, which in return regulates the EMT signaling pathway." (PMID 39998882, 2025). "For the downstream pathway, significant upregulation and downregulation of several genes, including SNAI1 and MMPs, in both cancer cell lines were identified, compared to the untreated group." (PMID 41226554, 2025). "The expression level and function of SNAI1 have been widely studied in many types of cancer, including CRC." (PMID 40613523, 2025). "CDH2, ZEB2, SNAI2, and SNAI1 are important regulatory genes that increase the motility and invasion capacity of cancer cells." (PMID 41179704, 2025).
cancer (continued). "The SMAD3/4 complex, in association with SNAI1, represses E-cadherin expression and enhances N-cadherin expression, thereby promoting EMT in cancer cells." (PMID 40134588, 2025). "As a characteristic metabolite of AM, UDP-glucose accelerates SNAI1 decay and impairs cancer metastasis." (PMID 38589585, 2024). "Subsequently, we isolated all the cancer cells and conducted an analysis of SNAI1 expression levels within these cells." (PMID 39702326, 2024). "SNAI1 is a zinc finger transcription factor that induces epithelial-mesenchymal transition (EMT) in various cancers and epithelial cells." (PMID 38329430, 2024). "SNAI1 was also deemed as an essential factor promoting the metastasis of various cancers through inducing EMT27." (PMID 38671227, 2024). "In this study, we analyzed the influence of altered ZEB1 and SNAI1 expression levels on cancer progression using a retrospective cohort of 51 intermediate-risk PCa tumors from FMRP-USP, Brazil." (PMID 38672562, 2024). "Zinc finger protein SNAI1 (also referred to as SNAIL) is a TF upregulated in cancer, which acts as a regulator of EMT in BC cells by repressing E-cadherin expression." (PMID 39275004, 2024). "NF-kB activation induces transcription of downstream genes involved in principal hallmarks of cancer; among of these, there are SNAI1 and ZEB1 that play a key role in EMT process." (PMID 38773406, 2024). "In a variety of cancers, the transcription factor Zinc finger protein SNAI1 induces an epithelial-to-mesenchymal transition (EMT) and a CSC-like phenotype." (PMID 38066386, 2024). "In view of the important role of SNAI1 in promoting cancer progression, targeting SNAI1 will be an attractive anti-cancer therapy." (PMID 39538371, 2024). "Cancer cells exhibiting elevated SNAI1 expression levels were also identified as having significantly higher scores in these signature models." (PMID 39702326, 2024). "To better understand the role of SNAI1 in maintaining cancer stemness, we included the CSC marker OV6 in the analysis." (PMID 39702326, 2024). "Whereas SNAI1 was equally expressed or slightly downregulated in the partial-EMT subgroups of basal-like cancers, ZEB1, ZEB2, and TWIST1 were more highly expressed in cluster 1 that is defined by the EMT-up genes." (PMID 38111531, 2023). "These miRNAs have been observed to target SNAI1 mRNA in a variety of cancers, resulting in its inhibition." (PMID 36980876, 2023). "In cancer-associated EMT, SNAI1 serves as an imperative factor in driving the transition by strongly repressing E-cadherin and tight junction components (claudins), while also upregulating mesenchymal marker proteins, including vimentin and fibronectin." (PMID 38144565, 2023). "In the majority of the 5 cancer types, PIK3CD expression was linked favorably with the expression of mesenchymal markers such as VIM (Vimentin), TWIST1, SNAI1 (SNAIL), SNAI2 (SLUG), and CDH2." (PMID 37861728, 2023). "Studies have reported that the downregulation of SNAI1 by miR-153 results in the suppression of cancer phenotypes, allowing for miR-153 to serve as a potential prognostic marker." (PMID 36980876, 2023). "A zinc-finger transcription inhibitor known as Snail family transcriptional repressor 1 (SNAI1) is involved in a wide range of physiological and pathological processes, such as healthy embryonic development, epithelial injury healing, and cancer spread." (PMID 36769171, 2023). "An opposite mechanism was also proposed showing that in non-invasive MCF7 cancer cells, SNAI1 directly represses expression of ERα expression, thus promoting EMT." (PMID 35290621, 2022). "miR-153 suppresses SNAI1-induced metastasis through negative regulation of SNAI1 in some types of cancer." (PMID 36158686, 2022). "Several genes associated with cancer cell motility, including SEMA5A, PDGFRB, TGFB2, CXCR4, SNAI1, ICAM1, and NEDD9, were decreased in shGPR81 cells." (PMID 35428832, 2022).
cancer (continued). "CircRNAs such as CircRBMS3, CircRNA-0084043 and Hsa-Circ-0008537 promote cancer cell migration, invasion and metastasis through upregulating SNAI1 and snail as a result of sponging miR-153 in melanoma, gastric cancer and liver cancer." (PMID 36158686, 2022). "On the other hand, genes related to cancer progression (Snai1 and Cdh1) were down regulated in tumors from immunized mice." (PMID 36366425, 2022). "Synuclein-γ (SNCG) and Snai1 play an important role in the occurrence and development of different types of malignant tumors." (PMID 35434126, 2022). "The expression of MYC, NR5A2, and SNAI1 was also higher in EC-adjacent tissues than in samples from cancer-free patients." (PMID 36140779, 2022). "Overexpression of SNAI1 sustains stemness maintenance and promotes invasion in numerous cancers, including CRC." (PMID 35847938, 2022). "Deubiquitinases (DUBs) counteract the SNAI1 degradation process to maintain a high level of SNAI1 protein in cancer cells." (PMID 34681726, 2021). "SNAI1 overexpression results in reduction of miRNA let-7 levels, and is sufficient to shift the phenotype of cancer cells tested toward stemness." (PMID 33806868, 2021). "m6A in the coding sequence of SNAI1 triggers polysome-mediated translation of SNAI1 mRNA in cancer cells." (PMID 34681726, 2021). "SNAI1, a zinc-finger transcription factor, is known to mediate the enhancement of proliferation and the inhibition of apoptosis in cancer cells." (PMID 33675467, 2021). "Given that cellular feedback mechanisms can eventually lead to drug resistance in cancer treatment, we proceeded to explore the role of SNAI1 in the development of resistance to triptonide treatment in TNBC." (PMID 33510281, 2021). "SNAI1 gene encodes for SNAIL protein, a major EMT-ATF transcriptional factor that plays a key role in inducing, cancer cell plasticity, chemoresistance and metastasis." (PMID 33674749, 2021). "Here, we discuss the regulation and role of SNAI1 in cancer metastasis, with a particular emphasis on epigenetic regulation and post-translational modifications." (PMID 34681726, 2021). "In mouse embryonic fibroblasts and human cancer cell lines, autophagy deficiency leads to the accumulation of the SQSTM1/p62 which by binding TWIST1 and SNAI1, leads to their stabilization and thereby increased migration and loss of epithelial markers." (PMID 34944948, 2021). "Because SNAI1, FN1, and MMP9 play a key role in inducing EMT-associated cancer plasticity, chemoresistance, and metastasis, we aimed to define the pivotal role of AURKA in mediating TGF-β-induced expression of SNAI1, FN1, and MMP9 genes." (PMID 33674749, 2021). "LRRC8A networks of cisplatin resistance are suggested to also include NOTCH and SNAI1, which are two transcription factors with high cancer relevance." (PMID 34638315, 2021). "We chose to focus on the EMT factor SNAI1 because of its role in reprogramming somatic cells to pluripotency and in cancer stemness." (PMID 33806868, 2021). "Although critical in normal development and wound healing, aberrant EMT has been linked to cancer metastasis, and over-expression of EMT drivers, such as SNAI1 and SNAI2, are associated with poor clinical prognoses in cancer." (PMID 33557266, 2021). "As expected, the transcription level of the SNAI1 gene was low in most cancer cell lines, except for the MIA Paca-2." (PMID 33804861, 2021). "Given the important role of SNAI1 in driving cancer progression, targeting SNAI1 would be an attractive anticancer therapeutic approach." (PMID 34681726, 2021). "To mechanistically address this issue, we generated a cancer cell-specific, dual deletion of both Snai1 and Twist1 by crossing SnailcKO; YFPLSL mice with KPC; TwistcKO; YFPLSL mice (KPC;ST)." (PMID 33852841, 2021). "Previous studies have established AKT and ERK as important inducers of SNAI1 transcription in cancer cells." (PMID 33510281, 2021).